BRCA1 (BRCA1 DNA repair associated)
Diseases named in the same sentence as BRCA1 in open-access papers (continued):
Sharing a sentence is not in itself a finding about the gene and the disease.
Obesity (46 papers, 2012 to 2026). Accumulation of substantial excess body fat. "Major risk factors include hormonal imbalance, radiation exposure, obesity, alcohol use, and Breast Cancer Gene 1 and 2 (BRCA1/2) mutations." (PMID 41502531, 2025). "The molecular mechanisms underlying a link between obesity and BC development in BRCA1/2 mutation carriers are still under investigation due to the multifaceted nature of obesity and the diverse oncogenic alterations that can drive BC molecular subtypes." (PMID 40523654, 2025). "While BRCA1/2 mutations are well‐documented as high‐penetrance risk factors for BC, the influence of obesity on cancer progression in these mutation carriers remains inadequately addressed and often unclear." (PMID 40523654, 2025). "Given the connection between obesity and cancer risk studies investigated the potential role of BRCA1 in regulation of lipogenesis and energy metabolism." (PMID 35432218, 2022). "The impact of obesity and diabetes on cancer risk in BRCA1 mutation carriers has been the topic of major clinical concern." (PMID 35432218, 2022). "Younger age, breast remodeling after weaning, obesity, exposure to ionizing radiation, BRCA1 mutation and AA race are all factors that affect the immune microenvironment of tissues including that of breast tissue." (PMID 34906209, 2021). "The main limitation of this study was the lack of an in-depth analysis of the cellular consequences of obesity-associated BRCA1 changes." (PMID 31940810, 2020). "Risk factors for the disease include race (men of African descent are at higher risk), genetics (e.g., BRCA1/2 mutations), and obesity." (PMID 32698438, 2020). "To identify short-term drivers of BRCA1 changes related to obesity we chose those cytokines most prominently associated with the pro-inflammatory environment of obesity and tested them in an in vitro villous explant culture model." (PMID 31940810, 2020). "Though few risk factors have been characterized, the best known include race (men of African descent are at higher risk), genetics (e.g., BRCA1/2 mutations), and obesity." (PMID 32698438, 2020). "In this study, we exploited scRNA-seq to investigate the impact of obesity on the microenvironment in the mammary gland of a mouse Brca1-deficiency cancer model." (PMID 32785175, 2020). "On this scenario, the relationship between obesity and BRCA1 mutations in UC patients should be further explored, even due to the necessity of understanding the potential role of Poly (ADP-ribose) polymerase (PARP) inhibitors in this tumor." (PMID 31443386, 2019). "Our findings are the first to suggest, to our knowledge, a close crosstalk between BrCa1, lipogenesis, adipogenesis, obesity, and obesity-associated insulin resistance." (PMID 22666314, 2012). "The growing prevalence of obesity, coupled with its established link to an increased risk of BC, underscores the urgent need for a deeper understanding of how these factors intersect, particularly in individuals with BRCA1/2 mutations." (PMID 40523654, 2025). "Therefore, several studies demonstrated an association with BRCA1 hypermethylation in women with obesity." (PMID 37512149, 2023). "The discrepancy could be due to population variations in competing risk factors such as genetic burden (e.g., BRCA1/2 mutations), hormone replacement therapy, and obesity, as well as protective factors such as multiple pregnancies and breastfeeding." (PMID 35206274, 2022). "We then aimed to determine which obesity-associated molecular mechanisms could explain the differences observed in placental BRCA1 levels between lean and obese women." (PMID 31940810, 2020). "Thus, further studies assessing the potential role of obesity-associated hyperinsulinemia on BRCA1 levels are warranted." (PMID 31940810, 2020).
Obesity (continued). "On the other hand, BrCa1 was found to be up-regulated in adipose tissue from obese subjects independently of whether they had T2D, so we suggest a crosstalk between BrCa1, lipogenesis, adipogenesis, obesity, and obesity-associated IR." (PMID 25922847, 2015). "Likewise, other maternal metabolic factors that could explain the obesity associated long-term effects on BRCA1 levels, e.g., hyperinsulinemia and insulin resistance, were not investigated in the present study and their contribution cannot be ruled out." (PMID 31940810, 2020). "Research indicated a remarkable upregulation of BRCA1 in the LW pig, signifying its pivotal role in modulating fatty acid and lipid metabolism, alongside controlling obesity." (PMID 38413888, 2024). "Total ovarian abundance of BRCA1, γH2AX, H3K4me, H4K5ac, H4K12ac, and H4K16ac (P > 0.05) was unchanged by obesity or dimethylbenz[a]anthracene exposure." (PMID 36702632, 2023). "In in vivo studies, BRCA1 was upregulated in adipose tissue from obese subjects together with phosphorylated ACCA and this data is consistent with the role of BRCA1 in limiting fatty acid synthesis during obesity." (PMID 33212987, 2020). "To subsequently characterize the effect of maternal obesity on specific cell cycle modulators, we selected BRCA1 as a potential candidate based on its consistent upregulation at the mRNA and the protein level." (PMID 31940810, 2020). "Five of the twenty-one obesity-dependent DEGs are associated with obesity and insulin resistance (MPHOSPH9, BRCA1, ASP, ALCAM, GP2)." (PMID 30305020, 2018). "In this study, we aimed to evaluate BrCa1 in human adipose tissue according to obesity and insulin resistance, and in vitro cultured adipocytes." (PMID 22666314, 2012). "Consistent with increased BrCa1 in obesity, increased P-ACC levels were shown in both SC (1.9-fold, p = 0.007) and OM (2.1-fold, p = 0.010) adipose tissue from obese subjects, and in SC when compared to OM fat depots (1.7-fold, p = 0.001)." (PMID 22666314, 2012). "It has previously been demonstrated that progressive obesity decreases BRCA1 abundance in mouse ovaries and in obese mice, there is dysfunction in ovarian ATM phosphorylation in an ovarian follicle stage dependent manner and a subsequent disconnect between ATM and H2AX phosphorylation." (PMID 36702632, 2023). "Obesity also decreased (P < 0.05) BRCA1 protein in primary follicle oocytes." (PMID 36702632, 2023). "The enhanced phosphorylation in obesity might reflect further BRCA1 interactions with other cell cycle regulators." (PMID 31940810, 2020). "Also, 4 of these DEGs have a known-role in placenta development and function (ALCAM, BRCA1 GP2, GSTA4) and 5 are associated with obesity and insulin resistance (MPHOSPH9, BRCA1, ASP, ALCAM, GP2)." (PMID 30305020, 2018). "Thereby, increased BrCa1 expression in obesity could be interpreted, as well as the reduced expression for many lipogenic factors, as the process through which cells reduce their ability to synthesize additional fatty acids once the storage capacity limit of the adipocytes is attained." (PMID 22666314, 2012). "The decreased activity of ACC in obesity may be accomplished by increased BrCa1 levels." (PMID 22666314, 2012). "Thus, to improve clinical management of BRCA1 and BRCA2 mutation carriers is necessary a deep knowledge concerning the impact of modifiable factors, as obesity, on BC risk, that may provide the oncologists additional recommendations for the care of patients with BC." (PMID 40523654, 2025). "When the total ovarian abundance of the gold standard indicator of DSB, γH2AX, and the DDR repair protein BRCA1 were measured in the ovary, they were unaffected by either DMBA exposure or obesity." (PMID 36702632, 2023). "Herein decreased BRCA1 in the oocytes of primary follicles due to both DMBA and obesity exposure was observed." (PMID 36702632, 2023).
Obesity (continued). "We hypothesized that obesity potentiates ovotoxicity through ineffective DDR, and investigated changes to abundance of DDR proteins, γH2AX, and BRCA1 and their distribution patterns in the ovary in lean and obese mice." (PMID 36702632, 2023). "Despite the overall effects of obesity on placental DNA methylation, placental BRCA1 methylation profile was not affected by maternal obesity in early pregnancy." (PMID 31940810, 2020). "The physiological increase in oxygen tension and DNA methylation do also not appear to drive BRCA1 upregulation in obesity." (PMID 31940810, 2020). "Additionally, obesity alone did not impact the abundance of BRCA1, γH2AX, H3K4me, H4K5ac, H4K12ac, or H4K16ac (P > 0.05)." (PMID 36702632, 2023). "Previously our group has reported a decrease in BRCA1 abundance with progressive obesity and in 10-week-old mice no observable changes in BRCA1 were noted suggesting that the alterations in BRCA1 previously noted could be age-related." (PMID 36702632, 2023). "Obesity-driven BRCA1 upregulation is not able to be explained by DNA methylation (EPIC array) or by short-term treatment of chorionic villous explants at 2.5% oxygen with tumor necrosis factor α (TNF-α) (50 mg/mL), leptin (100 mg/mL), interleukin 6 (IL-6) (100 mg/mL), or high glucose (25 nM)." (PMID 31940810, 2020).
hereditary cancer syndromes (43 papers, 2009 to 2026). "Alterations in homologous recombination pathway genes have been extensively studied in cancer, due to their high suitability for cancer hereditary syndromes in pathologic BRCA1/2 germline mutation carriers." (PMID 36358724, 2022). "Such basket trials not only focus on the gate keeper-type oncogene mutations, such as HER2 and BRAF, but also focus on the caretaker-type tumour suppressor genes, such as BRCA1/2, mismatch repair-related genes, which cause hereditary cancer syndrome." (PMID 33562094, 2021). "Ovarian epithelial tumors are an hallmark of hereditary cancer syndromes which are related to the germ-line inheritance of cancer predisposing mutations in BRCA1 and BRCA2 genes." (PMID 19825178, 2009). "PC may occur in individuals diagnosed with hereditary cancer syndromes caused by germline gene mutations (e.g., BRCA1/2, CDNK2A/p16)." (PMID 35761384, 2022). "The impact of DDR gene alterations on cancer formation is important in patients with hereditary cancer syndromes such as germline BRCA1/2 pathologic mutation carriers who have a higher relative risk incidence of breast, ovarian, uterine, and pancreatic cancers." (PMID 36358724, 2022). "With regards to the growing demand for FFPE tissue analysis, especially for the detection of BRCA1/2 mutations to guide clinical decision making and to identify patients with hereditary cancer syndromes, we consider optimization of CNV detection a major step in ensuring sufficient patient care." (PMID 31029168, 2019). "Cancer risk increases significantly throughout life in patients with hereditary cancer syndromes such as BRCA1/2." (PMID 41335382, 2025). "Individuals with proven hereditary cancer syndrome (HCS) such as BRCA1 and BRCA2 have elevated rates of ovarian, breast, and other cancers." (PMID 35877228, 2022). "The data presented here demonstrate that a large, population‐based tumor testing program in HGSC is effective in identifying BRCA1/2 PV both for the purposes of determining treatment eligibility, and as a potential screen for hereditary cancer syndromes." (PMID 33030818, 2021). "In the BRCA1 and BRCA2 genes, SNVs such as rs16942 and rs1799944 have been linked to increased BC risk, further underscoring the importance of comprehensive genetic analysis in managing hereditary cancer syndromes." (PMID 39710803, 2024). "However, effective identification of mutated high-risk cancer genes such as BRCA1 and BRCA2 depends on the availability of and access to genetic counseling and testing for people at high risk of a hereditary cancer syndrome." (PMID 39710803, 2024). "More recently, data from a large international consortium of families with hereditary cancer syndromes associated with BRCA germline mutations demonstrated that the relative risk (RR) of PDAC was 2.36 (95% CI, 1.51–3.68) for BRCA1 and 3.34 (95% CI, 2.21–5.06) for BRCA2." (PMID 35805011, 2022). "Nevertheless, the principal criteria for diagnosing hereditary PC remain as follows: PC at a younger age (up to 55 years), family members with confirmed germline BRCA1 and BRCA2 mutations, or presenting signs of hereditary cancer syndromes associated with mutations in DNA-repair genes." (PMID 32612654, 2020).
hereditary cancer syndromes (continued). "This led to the hypothesis that variants in BARD1 could encode an aberrant protein affecting the interaction with BRCA1 and predispose to BC and/or OC, especially in hereditary cancer syndrome families not accounted for by BRCA1 or BRCA2." (PMID 32726901, 2020). "Hereditary MTC is a different clinical context than other hereditary cancer syndromes (e.g., BRCA1, BRCA2), where penetrance is significantly lower, the genetic test can yield ambiguous results, and the effectiveness and perceived benefits of "treatment" is unknown or has significant side effects." (PMID 21436957, 2011). "Despite negative BRCA1 and BRCA2 test results, in certain cases, clinicians often remain suspicious of another hereditary cancer syndrome due to the family history of cancer." (PMID 28281021, 2017).
leukemia (41 papers, 2006 to 2025). A malignant (clonal) hematologic disorder, involving hematopoietic stem cells and characterized by the presence of primitive or atypical myeloid or lymphoid cells in the bone marrow and the blood. "Both AICAR and AMP inhibited RAD52 nuclear foci formation in BRCA-1-deficient leukemia cells after cisplatin-induced DNA damage." (PMID 36980703, 2023). "The degradation and loss of NSD2 stability promoted by BRCA1, induces hemin-dependent leukemia cell differentiation." (PMID 36232375, 2022). "Many recent studies, including ours, have shown that even if BRCA1/2 mutations are rarely detected in leukemias, PARPi-induced synthetic lethality can be effectively exploited in BRCA1/2-deficient hematopoietic malignant cells." (PMID 36497275, 2022). "A previous study confirmed that BRCA1/2-deficient leukemia cells were inhibited by the RAD52 inhibitor F79, which interferes with the DNA binding of RAD52." (PMID 33922657, 2021). "Among this list were several well-known risk factors for leukemia, such as BRCA1, RAD51, BMI1, and H3k27me3, demonstrating the effectiveness of our method." (PMID 32615918, 2020). "In keeping with this, BRCA1/2 germline mutation carriers have higher risk of developing certain leukemias and lymphomas." (PMID 32164626, 2020). "Rad52-/-Parp1-/- mice are normal but show delay in the appearance of BRCA1-deficient leukemia when compared to single knockout mice." (PMID 31615159, 2019). "In 2013, the first paper was published that confirmed the successful inhibition of RAD52 in human BRCA1/2-deficient leukemia cells derived from patients." (PMID 31615159, 2019). "PARPi was able to cause extensive “dual cellular synthetic lethality,” simultaneously eliminating DNA-PK-deficient quiescent leukemia CSCs and BRCA1/2-deficient proliferating CSCs and CPCs." (PMID 31615159, 2019). "It was shown that the aptamer caused synthetic lethality in those selected leukemia patient cells that had a low expression level of BRCA1 or RAD51C." (PMID 27649245, 2016). "Some epidemiologic studies show increased risks for leukemia/lymphoma in identified BRCA1 or BRCA2 mutation carriers and in large populations eligible for mutation testing." (PMID 17683622, 2007). "Similarly, targeting RAD52 has been demonstrated as a logical personalised synthetic lethal strategy in a range of FTK driven leukaemia types with associated impaired BRCA1/2." (PMID 38943005, 2024). "In addition, ABL1 kinase phosphorylates and regulates the activity of two DNA repair enzymes, PARP1 and RAD52, inhibition of which triggered synthetic lethality in BRCA1/2-deficient leukemia cells." (PMID 36959186, 2023). "BRCA1 mutations have also been implicated in the development of leukemia." (PMID 36551764, 2022). "The deficiencies that increase risk for leukemias and lymphomas may well be helpful in understanding other cancers in BRCA1/2 mutation carriers." (PMID 17683622, 2007). "In this case, NSD2 expression is inversely correlated to BRCA1 activity and erythroid differentiation in leukemia cell lines." (PMID 36232375, 2022). "Mechanistically, TGFβR kinase signaling stimulates the repair of DSBs in leukemia cells in the BMM via the upregulation of BRCA1/2, ATM, DNA-PKcs and LIG4." (PMID 36497275, 2022). "TIAR-mediated repression of BRCA1 mRNA translation is responsible for the downregulation of BRCA1 protein level in BCR-ABL1-positive leukemia cells." (PMID 35887183, 2022). "Our experimental results show that after treatment with Stattic, the level of ATM mRNA in leukemia cells is lower, and after Stattic and VP-16 treatment of cells, the expression of BRCA1, BARD1, RAD51, and polδ in the HR pathway are all downregulated." (PMID 33796529, 2021).